TNF (tumor necrosis factor)
Diseases named in the same sentence as TNF in open-access papers (continued):
Sharing a sentence is not in itself a finding about the gene and the disease.
Sepsis (continued). "However, the peak of TNF-α in this sepsis model was at 12 h." (PMID 37107001, 2023). "Indeed, the transcription of PRR genes, notably those of the Toll-like receptor (TLR) family are upregulated during sepsis, as well as pro-inflammatory cytokines such as tumor necrosis factor α (TNF-α), interleukins (IL)-1α, -1β, -6, and -12, and type-I interferons (IFN)." (PMID 36941625, 2023). "Many pediatric patients with sepsis develop innate and adaptive immune dysfunction, which is typically referred to as “immune paralysis” and can be identified by impaired whole blood ex vivo TNF-α and IFNγ production capacity in response to antigen stimulation." (PMID 36941659, 2023). "Certainly, ischemia-provoked myocardial TNFα production is significantly higher than sepsis-induced myocardial TNF production, and it may contribute to post-ischemic myocardial alteration by the inhibition of contractility as well as the triggering of myocyte hypertrophy and apoptosis." (PMID 36902036, 2023). "This sepsis-induced immunosuppression is typically characterized by dysfunctional monocytes, which show a decreased release of pro-inflammatory cytokines such as tumor necrosis factor α (TNFα), IL-1β and IL-6 upon stimulation with LPS and an enhanced secretion of anti-inflammatory IL-10." (PMID 37759239, 2023). "The protective effect of UFH/LMWH could be attributed to reducing the inflammatory response, such as NF-κB/MAPK dependent secretion of TNF-α and IL-6, and dampening endothelial and epithelial cell damage to protect against sepsis-induced kidney and lung injury." (PMID 36865384, 2023). "In the process of sepsis, cytokines such as TNF-α, IL-1β, and IL-6 mediated inflammatory response plays an important role, which may lead to endothelial and epithelial damage, affect vascular permeability and heart function, and eventually result in tissue necrosis and organ failure." (PMID 38152336, 2023). "miR-25-5p can improve brain injury caused by sepsis by inhibiting the thioredoxin-interacting protein TXNIP/NLRP3 pathway; reducing the levels of TXNIP, NLRP3, and cleaved caspase-1; and inhibiting the expression of inflammatory factors (such as IL-6, IL-1β, and TNF-α and peroxide)." (PMID 37629199, 2023). "Therefore, it suggested that SIN might protect against sepsis-induced MI via targeting TNF-α, IL-6, and IL-1β." (PMID 37388447, 2023). "In the early stage of sepsis, systemic activation of the innate immune system results in a severe and persistent inflammatory response characterized by an excessive release of inflammatory cytokines such as IL-1, TNF, and IL-17, collectively known as the “cytokine storm”." (PMID 37465127, 2023). "In the course of sepsis, DCs first transfer to the antigen epitopes of neutrophils, macrophages, and T helper lymphocytes (Th), activate NF-κB, enter the nucleus and form a complex with DNA, induce cell apoptosis, and release numerous proinflammatory cytokines and chemokines, such as TNF-α and IL-6." (PMID 36816800, 2023). "Either systemic or LyzCRE specific knock-out could alleviate the severity of sepsis mice, reduce the proinflammatory cytokine TNF-α and IL-1β expression in serum and decrease the monocytes number in bronchial alveolar lavage and peritoneal lavage via flow cytometry." (PMID 36707853, 2023). "Immediate early (IE) CMV gene, which is expressed by TNF-α stimulation, sepsis-induced immunosuppression, decreased IFN-γ T-cell responses, natural killer (NK) dysfunction, and impaired dendritic cell function all could be attributed to CMV reactivation after sepsis from a bacterial origin." (PMID 36765433, 2023). "However, initial clinical trials targeting TNF in sepsis patients yielded disappointing results." (PMID 38057824, 2023).
Sepsis (continued). "The loss of FDCs, GCs and impaired humoral immunity after interference with the TNF signaling using either TNF-neutralizing antibodies or gene-targeted mice has been described extensively in steady-state conditions and under inflammatory environments such as sepsis." (PMID 36950118, 2023). "Interestingly, in a study of 2634 sepsis patients, treatment with the anti-TNF antibody (Ab) afelimomab resulted in a modest but significant reduction in 28-day mortality if serum IL-6 levels were > 1000 pg/mL, while patients with lower IL-6 levels did not benefit from treatment." (PMID 38057824, 2023). "To determine whether Erbin-mediated autophagy regulates sepsis-induced inflammatory response and organ injury, we investigated the level of inflammatory cytokines TNF-α, IL-6, IL-1β, HMGB1, and IL-10 in polymicrobial sepsis mice and MDP-treated BMDMs with CQ treatment." (PMID 38105228, 2023). "MIF is a crucial factor in the development of sepsis, being involved in the recruitment of inflammatory cells such as macrophages, basophils, neutrophils, and eosinophils to the site of inflammation, resulting in an extensive release of different proinflammatory cytokines such as IL-1β and TNF-α." (PMID 38313162, 2023). "Therefore, TNF-α and IL-6 are recognized as proinflammatory cytokines for sepsis." (PMID 36110326, 2022). "Additionally, LR12 treatment protected mice from sepsis-induced vascular dysfunction, measured by improved vascular contractility, and attenuated IL-6, TNF-α, and IL-10 expression as well as NOS and COX signaling pathway activation in murine aortas and mesenteric arteries." (PMID 35784361, 2022). "In addition, sepsis-associated systemic inflammation was alleviated by the treatment of HO-1 inducers and CORM-2, as indicated by a drop of proinflammatory cytokines, including TNF-α, IL-1β and interferon-β." (PMID 35409029, 2022). "In this study, cytokines TNF, IL-6, IL-10, IFN-γ, IL-27, alarmins Hsp72 and Hsp90, and markers associated with inflammation (CRP, procalcitonin, lactate) and stress (glucose) exhibited early-onset induction, which was strongly correlated with an increased TOS/TAC ratio in sepsis." (PMID 35204114, 2022). "MiR-451a was positively associated with TNF-α (rs = 0.206, p = 0.026), IL-1β (rs = 0.209, p = 0.023), CRP (rs = 0.328, p < 0.001), and the APACHE II score (rs = 0.272, p = 0.003), while it did not relate to IL-6 (rs = 0.141, p = 0.129) in the patients with sepsis." (PMID 35992658, 2022). "However, recent studies have shown that TNF-α is also secreted by sepsis-stimulated cardiomyocytes." (PMID 34757596, 2022). "Polymicrobial sepsis may initiate myocardial cell depression via release of potent proinflammatory cytokines such as tumor necrosis factor (TNF)-α, interleukin (IL)-1β, and IL-6, which act as cardiodepressant mediators resulting in cardiac contractile dysfunction." (PMID 35190789, 2022). "Stimulated splenocytes from septic JAM-A–/– mice had decreased frequency of TNF+CD4+ cells and elevated frequency of IL-2+CD4+ cells, both of which could alter antimicrobial response and potentially play a causative role in improved survival from sepsis." (PMID 35819838, 2022). "These compounds exhibit protective effect on cardiac, lung, liver, and kidney against sepsis-induced acute organ damage, and several studies showed the ability of these phytochemicals to modulate cytokines related to inflammation such as IL-6, IL-1β, and TNF-α." (PMID 36588685, 2022). "Perhaps, the reduced MMP in neuron cells by BAM15 decreased the responses against LPS and cytokines (TNF-α) that limited sepsis-induced miR370-3p upregulation, resulting in less severe mitochondrial energy exhaustion, improved neuronal function, and reduced severity of sepsis encephalopathy." (PMID 35628259, 2022).
Sepsis (continued). "In addition, analyses of PBMCs from healthy volunteers in an endotoxin-tolerance model indicate that glucose metabolism supports leukocytes’ functions in a condition of immunomodulation, similar to sepsis, with both preserved (phagocytosis) and suppressed (TNF-α production) cellular responses." (PMID 36466921, 2022). "Moreover, according to research, significant endotoxemia in sepsis increases pro-inflammatory markers such as tumor necrosis factor-α (TNF-α), interleukin (IL)-1, IL-6, and IL-8, which are known for being thrombopoietic, meaning that it can increase platelet production." (PMID 35774677, 2022). "Thus, our findings indicated that DNA methylation changes in TNF-α gene along with aging may play a role in sepsis progression." (PMID 35242787, 2022). "In addition, previous studies suggested that PE treatment could decrease TNF-α and IL-6 levels in the plasma and alleviate myocarditis of sepsis rats." (PMID 36685596, 2022). "LP17 has also been shown to be an effective treatment for sepsis secondary to Pseudomonas aeruginosa pneumonia in rats, resulting in with improved hemodynamic status, attenuated lactic acidosis and hypoxemia, reduced serum TNF-α, IL-1β, and IL-6, and improved 7-day survival of the septic rats." (PMID 35784361, 2022). "TNF-α, IL-1β, and IL-6 are the major inflammatory factors that could contribute to sepsis." (PMID 36142743, 2022). "Thus, TNF-α and its related signaling pathways are important targets for the treatment of sepsis." (PMID 33967760, 2021). "Thus, the TNF promoter region might be one of the pivotal players in the progression and worst outcome of sepsis." (PMID 34692772, 2021). "Interestingly, both in vivo and in vitro human monocyte studies showed that in the hyperinflammatory acute phase of sepsis (6 h after sepsis induction), mitochondrial transplantation attenuated the hyperinflammatory reaction (TNF-α), indicating that it exerted an immunosuppressive effect." (PMID 33413559, 2021). "In the early stage of sepsis, to eliminate invading bacteria, macrophages are activated to become the M1 type, which produces a large number of proinflammatory factors, such as tumour necrosis factor (TNF)-α, interleukin (IL)-6, IL-1β, type I interferon, and chemokines." (PMID 34627385, 2021). "Hashad and colleagues reported that the heterozygous and minor homozygous genotypes (G/A and A/A) of TNF-α (–308 G/A) SNP were significantly different in AKI and non-AKI patients and both genotypes were an independent risk for AKI development in patients with severe sepsis." (PMID 34692772, 2021). "In addition to IL-6, early proinflammatory cytokines, such as TNF-α, IL-1, and IL-8 were studied to determine if their levels correlated with mortality from sepsis and septic shock, which are traditionally considered a consequence of an exacerbated early innate immune response." (PMID 33803628, 2021). "The exact pathophysiology of elevated RDW in sepsis is not well understood; however, it is possibly related to a systemic inflammatory response, leading to high levels of pro-inflammatory cytokines (e.g., interleukin-6, tumor necrosis factor-α) and increased oxidative stress in sepsis syndrome." (PMID 34441408, 2021). "Reduced expression levels of TNF-α, IL-1α, and C1qA were exhibited in the hippocampus of the berberine treatment group, and attenuated effect of declining neo-neuron, activation of microglia and astrocytes in the hippocampus of mice with sepsis were also found." (PMID 34867376, 2021). "In the acute phase of sepsis, macrophages polarize into the M1 phenotype to activate TLRs or other recognition receptors due to impaired intestinal barrier function, bacterial translocation, and increased inflammation, releasing a variety of inflammatory cytokines, such as IL-1β, IL-6, and TNF-α." (PMID 35003009, 2021).
Sepsis (continued). "Notably, LPS could react with toll like receptor 4 (TLR4), inducing phagocytic cells to generate a variety of proinflammatory cytokines, such as IL-1β, tumor necrosis factor α (TNF-α), and IL-6, which is suggested to be a key pathway in sepsis pathophysiology." (PMID 34055659, 2021). "A somewhat broader approach for direct sepsis treatment uses macrophage-like nanoparticles (NPs), consisting of a biodegradable polymeric NP core coated with cell membranes extracted from human macrophages to capture endotoxins such as lipopolysaccharide (LPS), IL-6, TNFα, and IFN-γ14." (PMID 34548486, 2021). "Several studies have reported that GTS-21 was a quite effective immunomodulatory drug and could attenuated pancreatitis disease, improved the survival rate of sepsis, reduced the level of TNF-related endotoxin in the lung and attenuated LPS-induced renal injury." (PMID 33815099, 2021). "This suggests that cogon grass root may ameliorate sepsis by increasing the platelet level, GPx3 activity, hepatocyte count, and cardiomyocyte count, as well as by reducing the lymphocyte count, monocyte count, TNF-α expression, and FABP4 level." (PMID 38559341, 2021). "Our results showed a close association between TNF-α production but not IL-1β or IL-6 with the NLRP3 29940 G>C variation in sepsis patients, which might be due to the complex inflammatory system in the host." (PMID 34172780, 2021). "Notably, early studies in rodents using TNF inhibitors showed promise with improved pancreatic pathology, and with positive outcomes also seen in sepsis patients, although their abundance of side-effects, likely due to TNFR2 inhibition, dampened enthusiasm for their further use." (PMID 34049483, 2021). "Diminished receptor expression for TNF-α (p55 and p75), observed by us after sepsis treatment, as well as for p55 following burn or mechanical injury therapy, may confirm TNF-α involvement in the pathomechanism of SIRS development initiated by infectious or non-infectious factors." (PMID 33672270, 2021). "Moreover, lncRNA TUG1 was downregulated in sepsis and might sponge miR-27a to downregulate expression of TNF-α, thereby inhibiting apoptosis of LPS-induced AC16 cells." (PMID 34055659, 2021). "Considering the possible relationship between inflammation and CLP-induced sepsis, the levels of IL-6, IL-10, and TNF-α in the PLF and blood obtained 8 and 24 h after CLP were measured in order to assess how omentum removal could affect cytokine production in response to infection." (PMID 33815381, 2021). "In consistent with these results, we demonstrated that the recruitment of JMJD3 and NF-κB in the promoter regions of TNF-α, IL-1β, and IL-6 contributed to the upregulation of these pro-inflammatory cytokines via H3K27me3 demethylation, thus promoting inflammatory response in sepsis." (PMID 33413595, 2021). "In a mouse model of cecal ligation and puncture (CLP) sepsis, rGas6 treatment reduced lung serum levels of proinflammatory cytokines, such as IL-6 and IL-17, and mRNA levels of proinflammatory cytokines and chemokines, such as TNF-α, IL-1β, IL-6, IL-17, and MIP-2, at 20 h post-CLP." (PMID 34829903, 2021). "Some studied sepsis-biomarkers include complete blood picture, C-reactive protein, serum amyloid A, lipopolysaccharide-binding protein, Interleukin 6 (IL-6), Interleukin 8 (IL-8), Tumor Necrosis Factor alpha (TNFa), procalcitonin, and Cluster of Differentiation 163 (CD163)." (PMID 34452099, 2021). "More than 2 decades on however, additional meta-analysis’ of data in sepsis patients revealed an overall improvement in survival rates, when studies are sufficiently powered, which likely prompted a re-examination of these traditional TNF inhibitors in patients with pancreatitis." (PMID 34049483, 2021). "Reportedly, CGP-60474 could inhibit IL-6 and TNFα to alleviate LPS-induced sepsis in mice." (PMID 34413339, 2021). "In addition to IL-18 TNF also represents a key mediator of sepsis and sepsis-induced organ injury." (PMID 35054259, 2021).
Sepsis (continued). "Baicalin could significantly reduce IL-1β in the sera of bacterial infected mice and could inhibit NLRP3 inflammasome activation through augmenting PKA signaling, thereby improving mouse survival in bacterial sepsis and could reduce the level of LPS, TNF-α, and IL-6 in the blood of sepsis mice." (PMID 34938184, 2021). "Additionally, sepsis severity in mice with subcutaneously implanted SE > CT catheters was more severe than in other groups as indicated by mortality rate, fungemia, serum cytokines (TNF-α and IL-6), and kidney and liver injury." (PMID 34746032, 2021). "TNF-α +489G/A SNP A-allele carriage may confer protection against sepsis and septic shock development but apparently does not influence sepsis-related mortality." (PMID 32171247, 2020). "In our high-dose TNF-α rats, exhaled p-cymol increased even earlier than lactate concentration, suggesting that p-cymol might facilitate early detection of inflammation and sepsis." (PMID 32549262, 2020). "Human studies showed higher levels of a pro-inflammatory mediator (tumor necrosis factor alpha) in men than women, and lower levels of an anti-inflammatory mediator (interlukin-10) in women, demonstrating the different immune reactions between genders during sepsis." (PMID 32271850, 2020). "Therefore, it is reasonable to hypothesize that inhibition of TNF-α represents a potential treatment option for sepsis in patients." (PMID 33679715, 2020). "Collectively, these data demonstrated that organ injuries mediated by TNF-α and the TNF-α/TNFR1 pathway during sepsis may involve mitochondrial injury/dysfunction and upregulation of the cell death processes of necroptosis, pyroptosis, apoptosis, and autophagy." (PMID 33003495, 2020). "Addition of PTX to GENT in neonatal sepsis, which resulted in significantly diminished TNF-to-IL-10 ratios in cerebral tissue of E. coli-infected mice in our study, might therefore be of particular benefit to protect the vulnerable neonatal brain from sepsis-induced inflammatory injury." (PMID 33072121, 2020). "Furthermore, the infectious burden and severity of sepsis were three times higher in Laroye's experiment compared to our study and the time course of pro-inflammatory cytokines, in particular TNF-α, markedly differed from our model, thus suggesting a different inflammatory environment." (PMID 32117276, 2020). "However, additional physiological functions contributed by THOP1−/− mice also included a better survival and performance behavior seven days after polymicrobial sepsis induction, with a slightly lower expression of TLR4 and TNF-α in dorsal hippocampus following the sepsis." (PMID 32847123, 2020). "However, if TNF doses last longer, as they may in persistent infections, sepsis or chronic inflammatory diseases, cells may die via necroptosis and thereby release DAMPs to fuel an overwhelming inflammatory response (Fig EV5A)." (PMID 33314666, 2020). "We selected some of the TNF-α and IL-17A targeting miRNAs based on knowledge of their involvement in modulating inflammatory response and using RT-qPCR, we confirmed upregulation of these miRNAs in sepsis intestinal epithelial EVs, compared with control intestinal epithelial EVs." (PMID 33182773, 2020). "MiR-19a may also participate in sepsis by targeting TNF-α, which a critical player in sepsis." (PMID 32944003, 2020). "The single nucleotide polymorphism (SNP) at position -308 in the promoter region of the TNF-α gene is the most studied in sepsis and has been associated with higher transcription rates of the cytokine and, more often than not, with an increased risk of sepsis." (PMID 32171247, 2020). "However, PDK1 deletion could decrease the level of TNFα in the late stage of sepsis as the opposite of the early stage." (PMID 32774145, 2020). "Moreover, administration of TNF-α induces a biological reaction similar to those of sepsis." (PMID 33679715, 2020).